FTH1 (ferritin heavy chain 1)
Diseases named in the same sentence as FTH1 in open-access papers (continued):
Sharing a sentence is not in itself a finding about the gene and the disease.
heart failure (12 papers, 2021 to 2025). Inability of the heart to pump blood at an adequate rate to meet tissue metabolic requirements. "Whereas in plasma from a heart failure model, miR-224-5p expression is upregulated, and it is believed to regulate iron metabolism and oxidative stress dysregulation-induced heart failure through the circSnx12/miR-224-5p/FTH1 pathway." (PMID 40997050, 2025). "FTH1-dependent ferroptosis responds to oxidative stress-mediated myocardial remodeling and heart failure." (PMID 37370086, 2023). "Recent studies found that FTH1 knockout mice spontaneously developed heart failure and induced cardiomyocytes ferroptosis through SLC7A11, confirming that the FTH1 is crucial in ferroptosis." (PMID 35677105, 2022). "In isoproterenol-induced heart failure, FTH1 protein levels are downregulated, while treatment with ATV impedes the downregulation of FTH1." (PMID 39742023, 2024).
gastric cancer (11 papers, 2020 to 2026). A primary or metastatic malignant neoplasm involving the stomach. "Previous studies have established that Stat3 interacts with the promoters of GPX4, SLC7A11, and FTH1, thereby modulating their expression levels in gastric cancer, which leads to the formation of a Stat3-ferroptosis regulatory axis." (PMID 41341590, 2025). "A similar effect was observed in gastric cancer cells treated with the STAT3 inhibitor W1131 caused by reduced STAT3 occupancy on the GPX4, SLC7A11, and FTH1 promoters." (PMID 38539832, 2024). "In this study, we found that PPI promoted the gastric cancer cell ferroptosis by regulating the NRF2/FTH1 axis given that the overexpression of NRF2 largely reversed the gastric cancer cell ferroptosis induced by PPI." (PMID 37081971, 2023). "Further studies revealed that NRF2/FTH1 pathways played an important role in PPI-induced cell ferroptosis in the gastric cancer." (PMID 37081971, 2023). "PPI also decreased the levels of nuclear factor erythroid 2-related factor 2 (NRF2) and ferritin heavy chain 1 (FTH1) in gastric cancer cells in vitro." (PMID 37081971, 2023). "In conclusion, we have demonstrated that PPI inhibits the gastric cancer growth by inducing the cancer cell ferroptosis via regulating the NRF2/FTH1 pathway." (PMID 37081971, 2023). "Our experimental results showed that EM combined with DDP significantly increased the levels of LPO, ROS, and divalent iron ions in MKN45/DDP cells while decreasing the levels of GPX4 and FTH1 proteins in the subcutaneous tumor-resistant nude mouse model of gastric cancer." (PMID 38345573, 2024). "Then, both HGC27 and HGC27/L cells were treated with different concentrations of baicalin for 24 h to explore the changes of key genes of ferroptosis, such as TfR, FTH1, GPX4 and IREB2 in gastric cancer cells exposed to baicalin with different concentrations." (PMID 38730240, 2024). "STAT3 knockdown in gastric cancer cells provoked a significant inhibition of GPX4, SLC7A11, and FTH1 at both the mRNA and protein levels, and also increased lipid peroxidation and ROS, and enhanced intracellular Fe2+, thus reducing the GSH/GSSG ratio in gastric cancer cells." (PMID 38539832, 2024). "In gastric cancer, STAT3 regulates ferroptosis primarily through its own histone acetylation, which increases its gene-level expression and promotes the expression of downstream direct targets GPX4, SLC7A11, and FTH1, thereby exerting an anti-ferroptotic effect." (PMID 41513612, 2026). "In gastric cancer, STAT3 directly bound to the promoters of negative ferroptosis regulators (GPX4, SLC7A11, and FTH1) and modulated their expression." (PMID 38341410, 2024). "In gastric cancer patients, STAT3 can bind to the consensus DNA response elements within the promoters of NR-related genes (GPX4, SLC7A11, and FTH1) and promote the expression of these ferroptosis-negative regulators, thereby establishing a negative STAT3–ferroptosis regulatory axis (Bottom left)." (PMID 41513612, 2026).
COVID-19 (10 papers, 2021 to 2026). A disease caused by infection with severe acute respiratory syndrome coronavirus 2. "We show for the first time that while serum ferritin in COVID-19 contained both FTH1 and FTL, it is predominantly composed of FTL." (PMID 41542049, 2026). "HEP6 and HEP7 cells had similar profiles to those in the HEP2 subset but with high expression of acute phase proteins in HEP7 (e.g., CRP, C3, C4a, SAA1, and FTH1; a COVID-19 specific cluster; below) or apoptosis and cellular senescence pathways in HEP6." (PMID 40087773, 2025). "Hence the FTH1 might be a potential network marker for COVID-19, which needed to be further studied in future." (PMID 37853311, 2023). "We analyzed the transcription of 9 major iron regulatory genes, among which FTL, ferritin heavy chain 1 (FTH1), and TfR1 are the most elevated genes in COVID-19 lung." (PMID 38769293, 2024). "We found that native serum ferritin protein in COVID-19 patients was composed of approximately 75.4 ± 10.35% FTL and 24.6 ± 10.35% FTH1 (SupplementaryFigure 10B), and that in individuals with ARDS who died had a trend for higher levels of FTL when compared to patients with ARDS who survived." (PMID 41542049, 2026). "Single-cell and bulk transcriptomic profiling of severe COVID-19 lungs further reveal upregulation of iron-regulatory transcripts (FTL, FTH1, TFRC) in pulmonary epithelial cells and macrophages, supporting a picture of tissue-specific iron dysregulation and enhanced ferroptotic vulnerability." (PMID 41516398, 2026). "BMDM Fth1 mRNA expression was increased following 72 hours of hyperoxia and trended towards a decline with further exposure, while Ftl mRNA expression was unchanged, mirroring PBMC FTH1 expression trajectory seen in human COVID-19 ARDS." (PMID 41542049, 2026). "Likewise, human endothelial cells treated with serum from COVID-19 non-survivors show increased ROS, elevated MDA/4-HNE, decreased GPX4, SLC7A11 and FTH1, all of which are reversible by Fer-1 or by blocking TNFR1 signalling." (PMID 41516398, 2026). "In addition, serum from coronavirus disease 2019 (COVID-19) non-survivors triggers ferroptosis in endothelial cells, which was manifested by elevated lipid peroxidation levels and decreased expression of GPX4, SLC7A11, and ferritin heavy chain (FTH1)." (PMID 39251905, 2024).
malaria (10 papers, 2014 to 2025). Malaria is a serious and sometimes fatal disease caused by a parasite that commonly infects a certain type of mosquito which feeds on humans. "In addition, we measured the expression of two genes that are known to have a hepatoprotective effect in the context of iron loading in malaria: Hmox1 (encodes haemoxygenase-1 (HO-1)) and Fth1 (encodes ferritin heavy chain)." (PMID 37812650, 2023).
prostate carcinoma (10 papers, 2018 to 2026). A carcinoma that arises from epithelial cells of the prostate gland. "The deregulation of both ICAM1, and FTH1 was previously associated with human prostate cancer." (PMID 30925701, 2019). "FTH1 and its pseudogenes are often suppressed in prostate cancer tissue samples, and this is suggested to occur through oncogenic miRNA-mediated down-regulation." (PMID 35447901, 2022). "A decreased FTH1 expression mediated by oncogenic microRNA (miRNA) has been reported in prostate cancer tissue samples." (PMID 35447901, 2022). "In DU145 and PC3 models of prostate cancer FTH1 and FTH1P11 and FTH1P16 show near equimolar expression level, further underlining the fulfilment of an important criterion for an effective parental gene:pseudogene ceRNA network." (PMID 33260500, 2020). "We here first time showed that FTH1 gene is up-regulated by curcumin treatment even after 48 h, consistent with its prostate cancer growth inhibitory functions." (PMID 31581661, 2019). "For example, FTH1 regulates tumorigenesis in prostate cancer, TP73-AS1 regulates proliferation in esophageal squamous cell carcinoma, and pseudogenes NKAPP1, MSTO2P, and RPLP0P2 are associated with poor prognosis in lung adenocarcinoma." (PMID 31029062, 2019). "A number of FTH1 pseudogenes have been shown to regulate FTH1 through ceRNA mechanism, involving multiple microRNAs and FTH1 pseudogenes, contributing to prostate cancer development and progression." (PMID 30071685, 2018). "An increase in FTH1 sequesters free iron, which reduces the growth of prostate cancer cells." (PMID 35447901, 2022). "Indeed, the FTH1 gene:pseudogenes network has been reported to be relevant in prostate cancer, possibly by affecting iron balance." (PMID 33260500, 2020). "The FTH1 query also resulted in the identification of pseudogenes (FTH1P2, FTH1P8, FTH1P11, FTH1P16) that regulate FTH1 in prostate cancer as well novel miRNAs that may be involved in ceRNA network regulation of FTH1 in prostate cancer." (PMID 31029062, 2019). "Downregulation of FTH1 resulted in prostate cancer development and progression." (PMID 31581661, 2019). "Moreover, in the context of prostate cancer and iron dysmetabolism, an FTH1 gene:pseudogene network appears capable of sequestering oncogenic miRNAs, interfering with competitively endogenous RNA (ceRNA) crosstalk, and effectively bearing out a tumor-suppressive function." (PMID 35447901, 2022). "SPH co-administered with bicalutamide demonstrated the significant up-regulation of FTH1 and down-regulation of TFRC, a gene expression profile unfavorable for further prostate cancer cell growth." (PMID 35447901, 2022). "Interestingly, in DU145 and PC3 models of prostate cancer, the addition of iron induced the expression not only of FTH1, but also of FTH1P11 and FTH1P16, two pseudogenes whose expression is not regulated by IREs, while iron depletion down-regulated FTH1, FTH1P11, and FTH1P16." (PMID 33260500, 2020).
acute kidney injury (9 papers, 2014 to 2026). Sudden and sustained deterioration of the kidney function characterized by decreased glomerular filtration rate, increased serum creatinine or oliguria. "Overloaded Fe2+ will then induce direct damage to proximal tubular lipid peroxidation through the Fenton reaction, leading to acute tubular necrosis or renal failure, where ferritin heavy chain 1 (FTH1) is of importance." (PMID 35860360, 2022). "The study indicated a protective role of FTH1 in proximal tubules in acute kidney injury." (PMID 33784251, 2021). "In IRI-induced acute kidney injury (AKI), H/R induces the ferroptosis of human proximal tubular epithelial cells (HK-2) through upregulating ACSL4 and COX-2, as well as down-regulating GPX4 and FTH1 in the kidney tissues." (PMID 37048123, 2023).
lung adenocarcinoma (9 papers, 2022 to 2025). A carcinoma that arises from the lung and is characterized by the presence of malignant glandular epithelial cells. "IGF2BP3 could stabilize a spectrum of anti-ferroptosis mRNA, including glutathione peroxidase 4 (GPX4), solute carrier family 3 member 2 (SLC3A2), acyl-CoA synthetase long chain family member 3 (ACSL3), and ferritin heavy chain 1 (FTH1), to inhibit ferroptosis in lung adenocarcinoma cells." (PMID 37554271, 2023). "In addition, from the UALCAN database, we found a slightly decreased level of FTH1 in the primary tumor of lung adenocarcinoma and lung squamous cell carcinoma compared to that in the normal one." (PMID 40538534, 2025).
neuroblastoma (9 papers, 2016 to 2025). Neuroblastoma (NB) is the most common solid, extracranial childhood tumor. "Our previous study showed that a shortage of FTH1 sensitizing the neuroblastoma cells to ferroptosis-inducers." (PMID 36012290, 2022). "In this study, we designed a novel gene reporter system which contained three copies of the sequence completely complimentary to miR-21 in the 3’ UTR of FTH1 for the MRI visualization of miR-21 in neuroblastoma." (PMID 34804934, 2021). "Neuroblastoma cell lines also express a very low level of ferritin heavy chain 1, whose reduction leads to a rise in ROS and a higher sensitivity to ferroptosis." (PMID 34926298, 2021). "To accomplish this, we genetically modified the ferritin heavy chain (FTH1) with a Tet-On switch and assessed the expression of FTH1 in transduced neuroblastoma cells (SK-N-SH) in vitro and in xenografted tumors in vivo." (PMID 27732930, 2016). "The antioxidant protein, FTH1 functions to store free iron and reduce iron‐mediated ROS production, and its overexpression suppresses erastin‐induced ferroptosis and ROS upregulation in neuroblastoma cells." (PMID 39369284, 2025). "Additionally, the expression of FTH1 mRNA is nearly 30 times higher in CAL33 than in neuroblastoma N2A cells, which are very sensitive to ferroptosis-inducers." (PMID 36012290, 2022). "A recent proteomic study revealed that upregulation of ATG7 was accompanied by the upregulation of ferritinophagy-related proteins, such as LC3, ferritin (FTL, FTH1), and NCOA4 in an arsenic trioxide-treated neuroblastoma cell line." (PMID 37522124, 2023). "Notably, due to insufficient FTH1, Erastin or RSL3 induces ferroptosis in neuroblastoma N2A cells, but fails to induce normal nerve cell death, indicating that ferroptosis may be a promising therapeutic target for neuroblastoma." (PMID 34858857, 2021).
osteosarcoma (9 papers, 2021 to 2026). A usually aggressive malignant bone-forming mesenchymal neoplasm, predominantly affecting adolescents and young adults. "A significant decrease in FTH1 indicates that osteosarcoma cells are more sensitive to chemotherapy." (PMID 40504108, 2026). "Another study revealed that the upregulation of miR-26a-5p can further target FTH1 mRNA and reduce FTH1 translation efficiency, significantly increasing the sensitivity of osteosarcoma cells to doxorubicin and cisplatin, thus improving drug efficacy." (PMID 39857292, 2025). "The increase in mature miR‐26a‐5p can further target FTH1 mRNA and eliminate FTH1 translation efficiency, increasing ferroptosis and promoting the sensitivity of osteosarcoma cells to chemotherapeutic drugs." (PMID 39979979, 2025). "METTL1 can upregulate mature miR-26a-5p, which then inhibits FTH1 mRNA translation efficiency; the decrease of FTH1 in turn increases ferroptosis and promotes chemotherapy sensitivity in osteosarcoma cells." (PMID 40725394, 2025). "A recent study reported that METTL1 triggers osteosarcoma cells ferroptosis via the miR-26a/FTH1 axis which in turn induces iron death and increases the sensitivity of osteosarcoma cells to chemotherapeutic agents." (PMID 38822363, 2024). "Interestingly, another study revealed that METTL1 reduces the FTH1 protein level by targeting pri‐miR‐26a and FTH1, evoking ferroptosis and promoting the sensitivity of osteosarcoma cells to chemotherapeutic treatments." (PMID 39979979, 2025). "However, METTL1/pri‐miR‐26a/ferritin heavy chain (FTH1) axis signalling enhances ferroptosis in osteosarcoma and strengthens the sensitivity of osteosarcoma cells to chemotherapeutic drugs." (PMID 39979979, 2025). "In this research, we detected the role of FANCD2 on ferroptosis of osteosarcoma cells, FANCD2 knockdown reduced the levels of FTH1 and GPX4, and elevated COX2, increased the levels of iron, LIP, Fe2+, and promoted lipid peroxidation." (PMID 36814203, 2023). "After DFO treatment, the protein expression of DMT1 not significantly changed in MNNG/HOS osteosarcoma cell, TfR1 was upregulated, and FPN, FTH1 and DMT1 were downregulated in osteosarcoma cells." (PMID 34281233, 2021). "In our study, after DFO treatment, TfR1 expression increased significantly, and FTH1, FPN and DMT1 expression decreased; however, DMT1 expression increased after DFX treatment in human osteosarcoma cells in vitro." (PMID 34281233, 2021). "Interestingly, decreased levels of METTL1 have been observed in osteosarcoma, with low METTL1 expression playing an oncogenic role through the regulation of ferroptosis mediated by the pri-miR-26a/FTH1 axis." (PMID 39870616, 2025). "We co-expressed nucleophosmin-1 (NPM1) fused to SspB (NPM1–mCherry–SspB), together with iLID fused to a multivalent (24-mer ferritin, FTH1) core and a nuclear localization signal (NLS–iLID–GFP–FTH1; GFP, green fluorescent protein), in human osteosarcoma (U2OS) cells." (PMID 38383656, 2024). "Similarly, DFX treatment led to a dose-dependent increase in the expression of TfR1 and the downregulation of FPN and FTH1 in MG-63, MNNG/HOS and K7M2 osteosarcoma cells." (PMID 34281233, 2021).
acute myeloid leukemia (8 papers, 2021 to 2024). Acute myeloid leukemia (AML) is a group of neoplasms arising from precursor cells committed to the myeloid cell-line differentiation. "Similarly, neratinib induces ferroptosis in acute myeloid leukemia (AML) cells, which is characterized by increased ROS and malondialdehyde content, enhanced Fe2+ activity, and downregulated GPX4 and ferritin heavy chain 1 expression." (PMID 38982494, 2024).
colitis (8 papers, 2020 to 2025). Inflammation of the colon. "Ferritin heavy chain was also of interest as ferritin heavy chain 1 is an anti-oxidative gene, and its upregulation was observed in a mouse colitis model fed with bioactive peptides with antioxidant properties compared to controls." (PMID 40943172, 2025). "Meanwhile, no apparent difference was observed in ferroptosis-related proteins between 2 groups of mice after DSS treatment, including ACSL4, GPX4, and FTH1, suggesting that ferroptosis contributed minimally to the aggravated colitis in Gab1IEC-KO mice." (PMID 36795486, 2023). "In a DSS‐induced colitis mouse model, the DSS group showed higher expression of ACSL4 and lower expression of GPX4 and FTH1 compared to the WT group." (PMID 41098076, 2025). "Moreover, the upregulation of anti-oxidative genes, including ferritin heavy chain 1, heme oxygenase 1, NAD(P)H quinone oxidoreductase 1, and superoxide dismutase 1, in the colons of colitis/SPH group was observed compared with the control peptide treatment group." (PMID 36139127, 2022).
diabetes (8 papers, 2022 to 2025). "A high expression of NCOA4 induced the degradation of FTH1 and then promoted free iron release, which is a crucial element to cause ferroptosis, in diabetes myocardial ischemia reperfusion injury." (PMID 38069270, 2023). "Our studies showed that TFR-1 expression was clearly increased, and FTH-1 expression was significantly decreased at both the protein and mRNA levels, indicating that iron homeostasis is imbalanced in diabetes." (PMID 36516169, 2022). "The expression of SLC7A11, GPX4, FSP1, FTH1, and FPN1 were suppressed, while TFR1 was elevated in the kidney injury induced by diabetes." (PMID 39630101, 2025). "Similarly, expression of A2M and FTH1 gene was significantly upregulated in diabetic PCOS females compared to females with complaint of BP (P < 0.001) and both diabetes and BP (P < 0.05)." (PMID 40057801, 2025).